SETD6 (SET domain containing 6, protein lysine methyltransferase)
Description:
Protein-lysine N-methyltransferase. Monomethylates 'Lys-310' of the RELA subunit of NF-kappa-B complex, leading to down-regulation of NF-kappa-B transcription factor activity. Monomethylates 'Lys-8' of H2AZ (H2AZK8me1). Required for the maintenance of embryonic stem cell self-renewal (By similarity). Methylates PAK4.
Synonyms: FLJ21148
Tractability: Small molecule: it has a binding pocket of medium quality. PROTAC: ubiquitination databases record sites on it.
Gene: Protein-coding gene on chromosome 16 (58,515,479 to 58,523,842, forward strand). Ensembl gene ENSG00000103037.
Subcellular location: Nucleus
Subcellular location (Human Protein Atlas): Nucleoplasm; Cytosol
Pathways (Reactome):
Chromatin organization: PKMTs methylate histone lysines
Gene Ontology:
Molecular function: NF-kappaB binding; protein binding; protein-lysine N-methyltransferase activity; S-adenosyl-L-methionine binding; histone methyltransferase activity
Biological process: peptidyl-lysine monomethylation; regulation of inflammatory response; stem cell differentiation; stem cell population maintenance; chromatin remodeling
Cellular component: nucleoplasm; nucleus
Genetic constraint (gnomAD): Loss-of-function variants: 67 observed, 50.02 expected, observed/expected ratio (o/e) 1.34, 90% interval 1.1 to 1.64. The synonymous counts are far from expectation, so gnomAD's model fits this gene poorly and the ratio says little. Missense variants: 712 observed, 575.46 expected, observed/expected ratio (o/e) 1.24, 90% interval 1.16 to 1.32. Synonymous variants: 307 observed, 231.67 expected, observed/expected ratio (o/e) 1.33, 90% interval 1.21 to 1.46.
Homologues: Orthologues: chimpanzee SETD6 (99% identical), macaque SETD6 (95% identical), pig SETD6 (87% identical), dog SETD6 (86% identical), rat Setd6 (80% identical), mouse Setd6 (79% identical), rabbit SETD6 (72% identical), guinea pig SETD6 (61% identical), tropical clawed frog setd6 (53% identical), zebrafish setd6 (46% identical). Paralogues in human: SETD3 (23% identical), SETD4 (17% identical).
Diseases named in the same sentence as SETD6 in open-access papers:
SETD6 is named in the same sentence as 24 diseases in open-access papers, as found by Europe PMC text mining. Sharing a sentence is not in itself a finding about the gene and the disease. The quoted sentences say what the papers report.
breast carcinoma (8 papers, 2014 to 2025). "Since SETD6 associates with ERα and nuclear receptor signaling factors, and regulates estrogen-responsive genes, we investigated the impact of SETD6 silencing on cellular proliferation of human breast carcinoma cell lines." (PMID 24751716, 2014). "We have previously shown that SETD6 specifically methylates BRD4 at K99 in a breast cancer cellular model, which in turn regulates the transcription of genes that control mRNA translation." (PMID 40809945, 2025). "SETD6 silencing also suppresses the oxygen consumption rate in breast cancer, and PAK4-K473 methylation attenuates adhesion." (PMID 40102573, 2025). "Conversely, SETD6 activity suppresses the proliferation of breast cancer, cervical cancer and osteosarcoma." (PMID 40102573, 2025). "In breast cancer cells, PAK4 methylation by SETD6 significantly attenuated cell adhesion by causing the mislocalization of paxillin, a PAK4 substrate, thereby promoting the disassembly of focal adhesions." (PMID 40102573, 2025). "Specifically, the silencing or knockout of SETD6 in mouse podocytes and triple-negative human breast carcinoma upregulates Nrf2 and augments the expression of antioxidant Nrf2 target genes." (PMID 40102573, 2025). "Collectively, our results suggest that methylation of PAK4 at K473 by SETD6 tunes the adhesion, migration and invasion properties of breast cancer cells." (PMID 33051544, 2020). "All breast carcinoma cell lines tested stopped proliferating upon silencing the expression of SETD6." (PMID 24751716, 2014). "Since SETD6 associates with nuclear receptor signaling-associated factors and ERα, we investigated the expression of known estrogen-responsive genes by qPCR in control and SETD6-depleted breast carcinoma cell lines." (PMID 24751716, 2014). "In agreement with the cell blockage induced by the silencing of SETD6, all breast carcinoma cell lines investigated expressed increased levels of CDKN1A in response to reduced expression of SETD6." (PMID 24751716, 2014). "However, in cervical and breast cancer, SETD6 has been shown to repress migration, as well as the invasive properties of the latter." (PMID 40102573, 2025). "The expression of SETD6 is amplified in about 10% of cases of breast cancer according to a study using a patient xenograft model and is required for cellular proliferation in both ER+ and ER− breast cancer cell models, suggesting an important role in driving breast cancer progression." (PMID 31370726, 2020). "While our study focuses on PAK4 methylation in breast cancer cells, it is known that PAK4 expression is associated with promoting cell migration and invasion in other cancers as well and it remains an open question if PAK4 activity in these cancers is also regulated by SETD6." (PMID 33051544, 2020). "In breast cancer, the methylation of MRPS23 by both SETD6 and PRMT7 regulates these cellular processes and controls metastasis." (PMID 40102573, 2025). "SETD6 was first identified as a KMT for histone H2AZ that controls expression of estrogen-responsive genes and proliferation in breast cancer cells." (PMID 30069008, 2018). "Interestingly, SETD6 is a required factor for the expression of endogenous PGR and TFF1, two estrogen-responsive genes, in certain breast cancer cell lines." (PMID 40102573, 2025).
bladder cancer (4 papers, 2017 to 2025). "In bladder cancer, SETD6 was reported to activate NF-κB signaling and promote urothelial cell survival." (PMID 36604642, 2023). "Another study reported that SETD6 is overexpressed in bladder cancer, where it stimulates NF-κB signaling by mediating methylation of p6542." (PMID 30069008, 2018). "We also found upregulation of SETD6 expression in other cancer cell lines (melanoma, pancreas and prostate) albeit at much lower level compared to bladder cancer cells." (PMID 28122346, 2017). "SETD6 protein level was 4-6 fold higher in bladder cancer tissue samples compared with the normal urothelial tissue (n = 9)." (PMID 28122346, 2017). "To determine the functional significance of SETD6 overexpression in bladder cancer cells, we tested the idea that SETD6 provides growth advantage to urothelial cells." (PMID 28122346, 2017). "In this study, we identified SETD6 as a significantly upregulated gene in bladder cancer cells and tissues." (PMID 28122346, 2017). "In keeping with our observations above, SETD6 knockdown inhibited survival of both bladder cancer cell lines and increased the percentage of cells undergoing death." (PMID 28122346, 2017). "Based on our data, we believe that SETD6 inhibition will have anti-cancer effects in bladder cancer." (PMID 28122346, 2017). "Our results show that primary urothelial cells and normal bladder tissue have nearly undetectable message and protein level of SETD6 that increases in transformed urothelial cells and is further increased in bladder cancer cells and tissues." (PMID 28122346, 2017). "Our results showed that SETD6 exerted its pro-survival effect in bladder cancer by positively regulating the NF-κB signaling pathway." (PMID 28122346, 2017). "To confirm the pro-survival function of SETD6 we used RNAi to knock down SETD6 in the bladder cancer cell lines, RT4 and UMUC3, (high endogenous levels of SETD6)." (PMID 28122346, 2017). "We identified a novel PKMT, SETD6, to be highly upregulated in bladder cancer cell lines and tissues at the mRNA and protein level." (PMID 28122346, 2017). "It is also possible that SETD6 methylated p65 recruits other activating cofactors which in turn activates an otherwise repressive methylation mark in bladder cancer." (PMID 28122346, 2017). "SETD6 knockdown in bladder cancer cell lines (UMUC3 and RT4) significantly decreased p65 levels suggesting that SETD6 regulates the protein level of p65." (PMID 28122346, 2017). "Our work has critical implications for the use of NF-κB as a therapeutic target in bladder cancer by inhibiting its regulator, SETD6." (PMID 28122346, 2017). "Message levels show that expression of SETD6 correlates with stage of bladder cancer, suggesting that SETD6 may have a role in bladder cancer progression." (PMID 28122346, 2017). "However, inhibiting SETD6 (epigenetic NF-κB modulator) that is upregulated in bladder cancer can be a potential therapeutic option to control the level of NF-κB in bladder cancer cells." (PMID 28122346, 2017). "Pro-inflammatory activity of NF-κB has been implicated in bladder cancer progression therefore, we speculate that inhibitors of SETD6 that can inhibit lysine methylation of p65 can be a potential therapeutic strategy for bladder cancer." (PMID 28122346, 2017). "To confirm the mRNA results, we used immunoblotting to determine SETD6 protein levels and found that SETD6 was minimally detectable in primary urothelial cells, higher in transformed bladder epithelial cells and > 50 fold higher level in bladder cancer cell lines compared with primary cells." (PMID 28122346, 2017). "Immunocytochemistry was used to determine SETD6 protein levels and it confirmed low basal level of SETD6 in the transformed cell line, SVHUC1, compared to bladder cancer cell lines." (PMID 28122346, 2017). "Examination of bladder cancer gene expression datasets failed to provide conclusive results regarding SETD6 expression in bladder cancer." (PMID 28122346, 2017).
bladder cancer (continued). "Validation of SETD6 expression using real-time qPCR showed low message levels in transformed (SVHUC1) and normal cells (HBLEC) and about 100 fold or higher expression in bladder cancer cell lines (T24, RT4, UMUC3)." (PMID 28122346, 2017). "Further, overexpression of SETD6 increased survival and growth of transformed bladder cells whereas knockdown in cancer cells reversed its effects on growth and survival suggesting a pro-survival function of this PKMT in bladder cancer." (PMID 28122346, 2017). "Although not conclusive, analysis of Oncomine data indicates a trend (non-significant) towards increased SETD6 copy number, expression with increased stage of bladder cancer and data from the TCGA suggests that SETD6 copy number may be affected by smoking status." (PMID 28122346, 2017).
prostate carcinoma (4 papers, 2023 to 2026). A carcinoma that arises from epithelial cells of the prostate gland. "In combined ChIP-seq and RNA-seq experiments, we observed differential transcriptional regulation in WT SETD6 WT or SETD6 KO prostate cancer cells expressing Flag-E2F1." (PMID 41540805, 2026). "In this study, the role of SETD6 mediated K117 monomethylation of E2F1 was investigated in prostate cancer cells." (PMID 41540805, 2026). "Chromatin immunoprecipitation (ChIP) data confirm that SETD6 impacts the binding of E2F1 and BRD4 at the same target loci, establishing a novel mechanism by which SETD6 methylation of E2F1 modulates gene regulation programs in prostate cancer cells." (PMID 41540805, 2026). "SETD6 KO GO Group 1 is related to cell proliferation and includes DHX37 and COX10, which both are associated with prostate cancer." (PMID 41540805, 2026). "While investigating the high expression level of SETD6 in prostate cancer, Kublanovsky and colleagues discovered that E2F1 occupies the SETD6 promoter and upregulates SETD6 mRNA expression." (PMID 40102573, 2025). "Overall, our data obtained with the SETD6 KO DU145 human prostate cancer cells clearly indicate that SETD6 has a key role in the establishment of H4K12me1 in human cell line." (PMID 38284488, 2024). "Further research is required to determine how SETD6 mRNA levels affect the malignant progression of prostate cancer." (PMID 37690684, 2023). "In our previous study, we identified E2F1 K117 as a novel SETD6 substrate in prostate cancer cells." (PMID 41540805, 2026). "Based on these data, we were interested to find out whether methylation of E2F1 K117 by SETD6 has a more general role in the regulation of gene expression programs in prostate cancer cells." (PMID 41540805, 2026). "Here, we explored how SETD6 methylation influences the E2F1 activity in prostate cancer cells." (PMID 41540805, 2026). "For this reason, we performed apoptosis and cell proliferation assays showing that SETD6 KO in prostate cancer cells reduced apoptosis and induced cell proliferation that could be partially connected to K117 methylation of E2F1." (PMID 41540805, 2026). "In addition to histone H2A isoforms, SETD6 was found to methylate histone H4 in vitro and in prostate cancer cells." (PMID 40102573, 2025). "Finally, H4-K12 mono-methylation was strongly attenuated upon SETD6 KO in the DU145 prostate cancer cell line." (PMID 40102573, 2025). "Finally, we document that SETD6 indeed is mainly responsible for introducing H4K12me1 in DU145 human prostate cancer cells." (PMID 38284488, 2024). "To test this hypothesis, we used DU145 prostate cancer cell lines stably expressing Flag-E2F1 WT or Flag-E2F1 K117R mutant in SETD6 WT and SETD6 KO context that have been described in our previous study and were characterized with respect to the expression of SETD6 and the different forms of E2F1." (PMID 41540805, 2026). "To demonstrate the SETD6-dependent binding of BRD4 and E2F1 in cells, we performed a GFP-trap assay in DU145 prostate cancer cells." (PMID 41540805, 2026). "In our previous study, we described that SETD6 methylates E2F1 at K117 in vitro and in prostate cancer cells." (PMID 41540805, 2026). "Further, additional studies are needed to understand the biological importance of this positive-feedback loop in prostate cancer as well as other cancer cell models that demonstrate a positive correlation between E2F1 and SETD6 gene expression levels." (PMID 40102573, 2025). "We show that SETD6 has a high H4K12me1 methylation activity (about 1000‐times stronger than HEMK2) and this enzyme is mainly responsible for H4K12me1 in DU145 prostate cancer cells." (PMID 38284488, 2024). "These distinct roles of E2F1 in the presence and the absence of SETD6 might explain previous findings pointing toward a conflicting role of E2F1 in prostate cancer, because in the light of our findings the effects of E2F1 on tumor progression depend on the SETD6 expression level of the cancer cell." (PMID 41540805, 2026).
glioma (2 papers, 2022 to 2025). A benign or malignant brain and spinal cord tumor that arises from glial cells (astrocytes, oligodendrocytes, ependymal cells). "SETD6 mRNA levels in patients with glioma are positively correlated with those of several transcription factors that are known to be involved in EMT, such as TWIST1." (PMID 40102573, 2025). "Other analyses have revealed that SETD6 expression is elevated in samples from patients with glioma and that high SETD6 expression is correlated with poor patient prognosis." (PMID 40102573, 2025). "Furthermore, RNA sequencing analysis of wild-type and SETD6-knockout glioma cells revealed that among downregulated genes there was a significant enrichment for those involved in EMT23." (PMID 40102573, 2025). "SETD6 positively influences the migration of glioma, lung adenocarcinoma and gastric cancer cells." (PMID 40102573, 2025). "When Twist1 is methylated by SETD6 (a methyltransferase), it will increase the occupancy of EZH2 (a histone lysine methyltransferase) and the catalysis of the repressive H3K27Me3 (histone H3 lysine 27 trimethylation) mark at the locus of lncRNA LINC-PINT (a tumor repressor in gliomas)." (PMID 36338770, 2022).
lung adenocarcinoma (2 papers, 2023 to 2025). A carcinoma that arises from the lung and is characterized by the presence of malignant glandular epithelial cells. "However, expression and function of SETD6 in lung adenocarcinoma (LUAD) remains unaddressed." (PMID 36604642, 2023).
melanoma (2 papers, 2017 to 2025). A malignant, usually aggressive tumor composed of atypical, neoplastic melanocytes. "The lysine methyltransferase SETD6 has been implicated in regulating transcription, cell adhesion, migration, and other processes in various cancers; however its role in melanoma remains unexplored." (PMID 40809945, 2025). "GO analysis revealed that the differential expressed genes are enriched in pathways such as cell proliferation and cell adhesion, two processes that are linked to melanoma as well as SETD6 enzymatic activity." (PMID 40809945, 2025). "Accordingly, alterations in cellular phenotypes, such as cell proliferation and adhesion, were seen after SETD6 KO, providing the first evidence of its involvement in melanoma." (PMID 40809945, 2025). "To test SETD6’s role in transcription regulation in melanoma, we performed RNA-sequencing experiments for control (CT) and KO of SETD6 in SKmel147 melanoma cells (four independent gRNA clones), which we have generated and validated by sequencing." (PMID 40809945, 2025). "Our data suggest that BRD4 binds MITF in melanoma cells and that this interaction is dependent on both SETD6-mediated methylation of BRD4 and MITF acetylation." (PMID 40809945, 2025). "Taken together, these results indicate that SETD6 influences gene expression profiles in melanoma cells, thereby promoting colony formation and cell adhesion." (PMID 40809945, 2025). "Kaplan–Meier survival analysis of 367 melanoma patients with low (n = 282) or high (n = 85) expression of SETD6 revealed that a high level of SETD6 correlates with poor patient prognosis." (PMID 40809945, 2025). "RNA sequencing revealed that SETD6 regulates the expression of genes that are related to various pathways in melanoma." (PMID 40809945, 2025). "Here, we provide evidence that BRD4 methylation by SETD6 at K99 plays an important role also in melanoma cells." (PMID 40809945, 2025). "The tight and significant correlation between the high SETD6 expression level and poor survival of melanoma patients led us to study its role in this cancer." (PMID 40809945, 2025). "Here, we observed that BRD4 methylation at K99 by SETD6 occurs in melanoma cells." (PMID 40809945, 2025). "Next, to test whether BRD4 is a substrate for methylation by SETD6 in melanoma, we used a lysine pan-methyl antibody in control and SETD6 KO cells." (PMID 40809945, 2025). "Given this role of BRD4 in melanocyte biology, we hypothesized that SETD6-mediated methylation of BRD4 would modulate the transcriptional program in melanoma cells." (PMID 40809945, 2025). "To address this hypothesis, we first immunoprecipitated endogenous BRD4 in melanoma cells and confirmed its interaction with endogenous SETD6 at chromatin." (PMID 40809945, 2025). "Altogether, these findings suggest that SETD6 binds and methylates BRD4 at K99 in melanoma cells to positively regulate cell proliferation and adhesion." (PMID 40809945, 2025). "However, the role of SETD6 in melanoma and the pathways through which it might act remain unclear." (PMID 40809945, 2025). "Here, we show that SETD6 binds and methylates BRD4 at K99 in melanoma cells to modulate the genomic distribution of BRD4 and MITF, and that BRD4 binds to MITF in vitro and in cells." (PMID 40809945, 2025). "In addition, we show that SETD6 interacts with MITF, a master transcription factor in melanocytes and melanoma, and influences the genomic distribution of MITF." (PMID 40809945, 2025). "Future work will reveal whether SETD6 and the methylation of BRD4 are also required for BRD4 and MITF transcriptional activity in regulating specific gene expression programs in melanoma." (PMID 40809945, 2025).